BCL2 (BCL2 apoptosis regulator)
Diseases named in the same sentence as BCL2 in open-access papers (continued):
Sharing a sentence is not in itself a finding about the gene and the disease.
Sepsis (continued). "It was observed that expressions of Bax, Cleaved caspase-3 and Cleaved caspase-9 were enhanced and Bcl-2 expression was decreased after the occurrence of sepsis." (PMID 34227919, 2021). "It has been reported that HOTAIR inhibited the apoptosis of kidney cells in a rat model of sepsis through downregulating of miR-34a/B-cell lymphoma 2 (Bcl-2) signaling pathway." (PMID 34630395, 2021). "The number of naïve and memory CD8+ T cells is reduced by sepsis-induced apoptosis, as indicated by increased caspase 9, Bim, and Bid expression and decreased Bcl-2 expression in CD8+ T cells isolated from patients with sepsis." (PMID 33532141, 2021). "LPS upregulated Bax and cleaved caspase-3 and downregulated Bcl2 in sepsis; however, these effects were attenuated by APN." (PMID 34084134, 2021). "Sepsis-induced myocardial injury significantly increased the expression of cleaved-caspase-3 and Bax and decreased the expression of Bcl-2, compared with that in the sham group." (PMID 33819192, 2021). "In a murine model of sepsis, IL-7 treatment resulted in the upregulation of the anti-apoptotic protein Bcl-2 and downregulation of pro-apoptotic proteins such as Bim and Puma." (PMID 32197507, 2020). "We found that GSS effectively inhibited the sepsis‐induced BCL‐2 decrease and caspase‐3 activation in lung tissue." (PMID 31756053, 2020). "In mouse models of sepsis, administration of IL-15 can significantly inhibit sepsis-induced apoptosis of immune competent cells through boosting Bcl-2 expression." (PMID 32197507, 2020). "In a previous study, LY294002 was used to study the myocardial protective role of PI3K/AKT signal in septicemia, and it can induce the expression of Bcl-2 and decrease the expression of Bax, suggesting that it has an inhibitory effect on apoptosis." (PMID 33343353, 2020). "In experimental models of sepsis, IL-7 was responsible for regulating BCL2 to block lymphocyte apoptosis, restoring IFN-γ production and improving recruitment of immune cells to the infection site." (PMID 32479514, 2020). "Bcl-2 transgenic mice exhibited limited number of DC apoptosis and improved their survivability during severe sepsis in comparison with wild type mice." (PMID 32197507, 2020). "The ratio of cleaved Caspase-3/Caspase-3 and Bax/Bcl-2 expression was increased in mice of the sepsis group, and heparin dramatically reduced the levels of apoptotic proteins." (PMID 33344474, 2020). "Transgenic mice with T cell overexpression of Bcl-2, a potent anti-apoptotic protein, were protected against sepsis-induced T cell apoptosis in the thymus and spleen and had greater levels of systemic inflammatory cytokines and higher survival." (PMID 33336293, 2020). "In contrast, in rats anesthetized with isoflurane +sepsis, inflammation led to significant increases in the hepatic expression of HO-1 (58%), iNOS (92%), and bcl-2 (74%) proteins." (PMID 33392215, 2020). "According to our results, simvastatin similarly as ulinastatin, a protease inhibitor, attenuated splenic T-cell apoptosis and increased anti-apoptotic Bcl-2 expression in abdominal (CLP) sepsis and burn injury." (PMID 30828299, 2019). "In sepsis, IL-15 attenuated the apoptosis rate of intestinal epithelia and increased Bcl-2 and IFN-γ expression in IECs as well as the natural killer cell population, which produced further IFN-γ." (PMID 31114571, 2019). "The first study to report that prevention of apoptosis improved the survival in sepsis showed that Bcl-2 overexpression is more resistant to sepsis-induced apoptosis." (PMID 31611560, 2019). "In our study, we indicate that the expression levels of the ER stress markers p-eIF2α and GRP78 and two factors involved in ERS-related apoptosis, CHOP and Caspase-3, were increased, and the BCL-2 : BAX ratio was decreased during sepsis." (PMID 31263382, 2019). "The downregulation of Bcl-2 and upregulation of Bax resulted in a significant decrease in the ratio of Bcl-2/Bax induced by sepsis." (PMID 26904148, 2016).
Sepsis (continued). "Our results raised the possibility that YAP/P73/(BAX and BCL-2)/caspase-3 pathway played an important role in regulating HPMEC apoptosis in sepsis-induced ALI." (PMID 27807512, 2016). "Studies have proved that the BAX expression of lung is increased and BCL-2 expression of lung is decreased in sepsis-induced ALI model in mice." (PMID 27807512, 2016). "Accordingly, the Bcl-2/Bax ratio appeared to increase in rats with sepsis in response to exogenous Hsp72." (PMID 26221596, 2015). "The sepsis-induced decrease in Bcl-2 expression was reduced by 49% (∗p < 0.05) after rhHsp72 administration (comparison between empty and shaded columns)." (PMID 26221596, 2015). "Bcl-2 is an antiapoptosis mediator, whereas Bax is a proapoptosis mediator; therefore, the results suggest that rhHsp72 reduces liver apoptosis during sepsis progression." (PMID 26221596, 2015). "Bcl-2 expression decreased by 41% (∗∗p < 0.01) during sepsis (comparison between empty and black columns)." (PMID 26221596, 2015). "During experimental sepsis, IL-7 decreases cell apoptosis through the expression of antiapoptotic Bcl-2 gene." (PMID 25614712, 2014). "Median Pre-operative Bcl-2 mRNA copy numbers were similar to those of bacteraemic patients and healthy controls, and greater than patients with sepsis (Wilcoxon rank sum test P < 0.0001)." (PMID 21711552, 2011). "Bcl-2 gene expression was less (P < 0.0001) and Bim gene expression was greater (P = 0.0003) in severe sepsis compared to bacteraemic and healthy controls." (PMID 21711552, 2011). "There was no relation between severity of organ failure and/or outcome in patients with sepsis and IL-2, IL-7, IL-15, Bim, Bax or Bcl-2 gene expression." (PMID 21711552, 2011). "In multiple studies transgenic mice over-expressing BCL2 in various target cells have decreased apoptosis and improved survival in sepsis." (PMID 21390214, 2011). "Treatment with rhBCL2A1 or rhBCL2 protein protects mice from sepsis by reducing apoptosis in multiple target tissues, demonstrating an unexpected, potent activity of extracellularly administered BCL2 BH4-domain proteins." (PMID 21390214, 2011). "On post hoc testing Bcl-2 gene expression was significantly lower in PBLs of patients with sepsis compared with controls, after culture in the presence of αCD3ab and rIL-2 (P = 0.005)." (PMID 21711552, 2011). "We investigated the effect of extracellular administration of two anti-apoptotic members of the BCL2 (B-cell lymphoma 2) family of intracellular regulators of cell death in a murine model of sepsis induced by cecal ligation and puncture (CLP)." (PMID 21390214, 2011). "By contrast, the pro-survival members Bcl-2 and Bcl-xl were both downregulated in severe sepsis (p < 0.001 and p < 0.05, respectively)." (PMID 18925930, 2008). "Recently, inhibition of mitochondrial membrane permeability transition using immunosuppressive agents or mitochondrial Bcl-2 overexpression has been shown to inhibit sepsis-induced myocardial dysfunction and mortality in a mouse model." (PMID 18560574, 2008). "The mRNA expression of Bcl-2 was markedly downregulated in patients with severe sepsis as compared with healthy controls." (PMID 18925930, 2008). "Overexpression of Bcl-2 or adoptive transfer of Bcl-2 overexpressing lymphocytes in murine models reduces mortality from caecal ligation puncture-induced sepsis." (PMID 18925930, 2008). "In CD4+ T-cells (p < 0.05) and B-cells (p < 0.001) the Bcl-2 protein was decreased in severe sepsis." (PMID 18925930, 2008). "Another mechanism for the downregulation of Bcl-2 and Bcl-xl in sepsis has been described recently by Groesdonk and colleagues." (PMID 18925930, 2008). "As the intrinsic pathway is controlled by members of the mitochondrial membrane-bound Bcl-2 family, previous studies on patients with sepsis and shock have demonstrated an essential role of the anti-apoptotic Bcl-2 protein for cell survival." (PMID 18211685, 2008).
Sepsis (continued). "Notably, the current study depicted that CLM markedly downregulated Bax, and caspase-3 gene expression, and conversely stimulated the Bcl-2 gene expression indicating its anti-apoptotic impact during sepsis." (PMID 40770673, 2025). "Highlighting the potential of targeting gut epithelial apoptosis, gut-specific overexpression of the anti-apoptotic Bcl-2 in transgenic mice not only reduced sepsis-induced cell death, but it also reduced hyperpermeability and improves survival following intra-abdominal sepsis." (PMID 40098052, 2025). "H2S alleviated sepsis-induced acute kidney injury by inhibiting PERK/Bax-Bcl2 pathway." (PMID 40989844, 2025). "MVA-hIL-7-Fc can induce higher Bcl-2 levels than rhIL-7 in the lungs and spleens of sepsis mice." (PMID 41158471, 2025). "In sepsis models, genetic ablation of SIRT3 has been associated with intensified apoptotic responses, as evidenced by increased Bax and caspase-3 levels alongside reduced Bcl-2 expression." (PMID 40860195, 2025). "During sepsis, Bcl-2 up-regulation prevents lymphocyte apoptosis." (PMID 38419887, 2024). "Moreover, necroptosis and pyroptosis (another form of PCD) pathways collaborated to aggravate tissue injury in the process of sepsis, and BCL2 constrained the induction of these two pathways through interaction with a BCL2-homology-3 like domain." (PMID 38894720, 2024). "In the heart, IRF9 expression was upregulated in sepsis, while BCL2 was downregulated." (PMID 38894720, 2024). "We observed that resveratrol, both in its native form and encapsulated within silver nanoparticles, could substantially mitigate the sepsis-induced changes in the expression of Bcl-2, Caspase-3, TLR4, IL-1Β, and TNF-α." (PMID 38546748, 2024). "However, sepsis induction (CLP group) precipitated a significant plunge in Bcl-2 expression, providing clear evidence of escalated cell apoptosis in the septic state." (PMID 38546748, 2024). "In conclusion, using machine learning analysis we identified 4 necroptosis-related hub genes (BACH2, GATA3, LEF1, and BCL2), which could be used as the potential di-agnostic and prognostic biological marker in sepsis." (PMID 37091800, 2023). "The expression of the proteins Bax, Cleaved-Caspase 3, Cleaved-Caspase 9, Cytochrome C, and Cleaved-PARP were significantly increased, whereas the expression of Bcl-2 was significantly decreased in the myocardium of rat with sepsis as compared with the Sham group at the same point of time." (PMID 37219401, 2023). "In a model of sepsis caused by cecal ligation and puncture, emodin protected the jejunum in rats with sepsis by activating JAK1/STAT3 signaling pathway and regulates apoptosis proteins (Bcl-2 and Bax) expression." (PMID 35744949, 2022). "The Shenfu formula can resist myocardial cell apoptosis by inhibiting the protein expressions of Fas, Fas-L, Bcl-2, and Bax, which may slow down the process of sepsis." (PMID 36438846, 2022). "Thus, the modulatory effect of menthol, and possibly other TRPM8 agonists, on Bcl2 expression and function, and its effect on the prognosis of sepsis is intriguing and needs further investigation." (PMID 35814769, 2022). "Compared to the untreated sepsis group, menthol exhibited remarkable anti-apoptotic activity reflected by a significant (p < 0.05) decline in hepatic cleaved caspase-3 expression and enhanced expression of Bcl-2 in treated septic rats." (PMID 36120368, 2022). "Overall, lncRNA SNHG1 regulated the DNMT1/Bcl‐2 axis to promote sepsis‐induced myocardial injury." (PMID 35678255, 2022). "Sepsis induced a significant increase in Bax and a decrease in Bcl-2 levels." (PMID 36333747, 2022). "Of note, a prior study revealed that increased Bcl‐2 expression in mouse liver tissues following pretreatment with SDF‐1 aided in the therapeutic functions of endometrial regenerative cells on ameliorating sepsis symptoms." (PMID 35678255, 2022).
Sepsis (continued). "Moreover, patients with sepsis or septic shock exhibit lower levels of the mitochondrial anti-apoptotic protein B-cell lymphoma 2 (BCL2) in their lymphocytes." (PMID 34216304, 2021). "Our data identified IL-38 as a potent inhibitor of sepsis-induced macrophage apoptosis, evidenced by downregulation of apoptosis, Bax, and cleaved caspase 3, with upregulation of Bcl-2 level, leading to an increase in the Bax/Bcl-2 ratio." (PMID 34955683, 2021). "One of the possibilities might be that cell death in CD4 lymphocytes in patients with sepsis was mainly via apoptosis since TLR4 inhibition could elevate the Bcl2 to Bax ratio to suppress apoptosis." (PMID 34733114, 2021). "PVT1 knockdown could induce apoptosis in lipopolysaccharide-induced H9c2 cells, through up-regulating Bax and caspase-3 and down-regulating Bcl-2, thereby exerting functional roles in sepsis-induced myocardial depression." (PMID 34775377, 2021). "We confirmed experimentally that lentinan could significantly reduce the protein expression of NF-κB as well as TLR4, NF-κB, and Bax, but increase the expression of occludin and Bcl-2 in intestinal tissue of mice with gut-origin sepsis." (PMID 34790828, 2021). "Recently, it was shown that overexpression of BCL-2 could prevent depletion of DCs, and preventing DC death in mice was shown to offer resistance to endotoxin-induced sepsis." (PMID 33336293, 2020). "Taken together, our results demonstrated that GSS might be a promising candidate for sepsis‐induced ALI via its regulating effects on Myd88/NF‐κB/BCL‐2 signalling in lung ECs." (PMID 31756053, 2020). "Consistent with the data obtained from western blotting analysis, our PCR results also showed that, although the ratio of Bax/Bcl-2 gene expression was dramatically increased in mice of the sepsis group, the ratio decreased in samples from the heparin intervention group." (PMID 33344474, 2020). "To further determine whether GSS inhibits sepsis‐induced lung vascular EC apoptosis in vivo, we used immunoblot analysis and immunofluorescence microscopy to determine the changes in lung BCL‐2 expression, caspase‐3 activation and lung vascular EC apoptosis." (PMID 31756053, 2020). "Furthermore, GSS not only reversed the sepsis‐induced BCL‐2 changes in expression in mouse lungs but also blocked sepsis‐associated lung vascular barrier disruption and ALI in vivo." (PMID 31756053, 2020). "Interestingly, in mouse models of sepsis the transgenic expression of Bcl-2 in a variety of cell types reduces cell death and improves survival." (PMID 31839993, 2019). "In addition, when anti-apoptotic proto-oncogene Bcl-2 was gut-specifically overexpressed, a decrease in sepsis-induced intestinal epithelial apoptosis was found in murine models." (PMID 31114571, 2019). "MicroRNA 195, a regulator of Bcl-2 gene expression, which assists in maintaining the pro/anti-apoptotic balance, has been shown to be upregulated in murine sepsis and its inhibition could prevent apoptosis and even the development of MODS." (PMID 31114571, 2019). "IL-7 also causes many desirable changes in T lymphocytes (that may prove beneficial) in the context of sepsis disease progression, including: upregulation of Bcl-2 proteins and resistance to apoptosis, proliferation and enhanced function." (PMID 31281814, 2019). "Moreover, it is important to note that sepsis decreases the level of expression of BCL-2 and increases in Bax expression which contributes to apoptosis." (PMID 30271451, 2018). "Furthermore, our results revealed that hemin alleviated intrapulmonary cell apoptosis, elevated the Bcl-2 level, and reduced Bax expression in lung after sepsis." (PMID 30013453, 2018). "Also in the vestibular system a moderate staining of BCL-2 was observed in sepsis mice in the utricle." (PMID 28404559, 2017).
Sepsis (continued). "On the other hand, in our sepsis model we also found the expression of Bcl-2 of cardiac tissues were increased by Thaliporphine, which could counteract LPS induced apoptosis (data not shown)." (PMID 22761733, 2012). "In cultured PBLs, IFN-γ gene expression was decreased in response to LPS and increased in response to CD3ab with sepsis: IL-7 gene expression increased in response to LPS in controls and to CD3ab with sepsis; Bcl-2 gene expression decreased in response to combined CD3ab and IL-2 with sepsis." (PMID 21711552, 2011). "Thus, increased intracellular BCL2 in multiple lineages is able to confer protection in experimental sepsis." (PMID 21390214, 2011). "Bcl-2 gene expression was greatest in bacteraemic patients, intermediate in controls and the least in septic patients; Bim gene expression was increased in sepsis compared to bacteraemia and controls; Bax gene expression was similar in all three groups." (PMID 21711552, 2011). "The link between sepsis and lymphocyte apoptosis is well established, with several investigators reporting down-regulation of gene expression of the anti apoptotic protein Bcl-2 and upregulation of gene expression of antagonistic pro-apoptotic proteins, such as Bid and Bax." (PMID 21711552, 2011). "Indeed, we found that administration of BCL2 protein alone was sufficient to reduce sepsis-induced lethality (manuscript in preparation)." (PMID 20161703, 2010). "Indeed activation of AKT/protein kinase B, extracellular regulated signalling kinase and Bcl-2 improves survival in sepsis and these effectors are upregulated by dexmedetomidine." (PMID 19691839, 2009). "In our study we confirmed the downregulation of Bcl-2 in severe sepsis." (PMID 18925930, 2008). "In patients, Bcl-2 expression was found to be decreased during sepsis." (PMID 18925930, 2008). "During sepsis, excessive production of mitochondrial ROS disrupts hepatocyte mitochondrial function, leading to the activation of pro-apoptotic signalling pathways, including Bax/Bcl-2 imbalance, cytochrome c release and caspase activation, ultimately leading to apoptosis." (PMID 41319591, 2025). "Within the PI3K-AKT pathway framework, AKT1 enhances the anti-apoptotic function of BCL2 gene by phosphorylating and inhibiting pro-apoptotic proteins, highlighting the synergistic role of these two genes in regulating the immune response to sepsis and COVID-19." (PMID 41411324, 2025). "Vincamine exhibited hepato-protective potential during CLP-induced sepsis via the cross-connection of antioxidant, anti-inflammatory, and anti-apoptotic activities by modulating TNFα/IL-6/IL-1β/Nrf-2/Keap-1 and regulating bax/bcl2/cleaved caspase 3 signaling pathways." (PMID 39174578, 2024). "Furthermore, we found that the protein expression levels of Bax, Caspase-3, and Caspase-9 were significantly lower, and the protein expression levels of Bcl-2 were significantly higher in Group B. These results indicate that PTX3 inhibits the apoptotic ability of cardiomyocytes in sepsis." (PMID 38784395, 2024). "IFNγ could also promote Bcl-2 and inhibit Bax expression in sepsis." (PMID 37434129, 2023). "Therefore, Bax and Bcl-2 protein levels in the lungs of CLP sepsis mice were examined (n = 6)." (PMID 37978525, 2023). "Thus, we aimed to determine whether esmolol could reduce sepsis-induced peripheral blood mononuclear cell (PBMC) apoptosis by modulating Akt/Bcl-2/Caspase-3 pathway." (PMID 36852973, 2023). "Therefore, we made a hypothesis in the present study that lncRNA SNHG1 may orchestrate the DNMT1/Bcl‐2 axis to affect the sepsis‐induced myocardial injury." (PMID 35678255, 2022). "Similarly, the relative levels of Bax, a proapoptotic protein that can release apoptosis-promoting substances into the cytoplasm, and Bcl2, an antiapoptotic protein that blocks oligomerization of proapoptotic proteins, suggested that sepsis is correlated with increased apoptosis." (PMID 35722155, 2022).